RAD51 (RAD51 recombinase)
Diseases named in the same sentence as RAD51 in open-access papers (continued):
Sharing a sentence is not in itself a finding about the gene and the disease.
cancer (continued). "In this study, we interrogated RS through the prism of tumor-cell heterogeneity by measuring its level in breast CSCs (bCSCs) compared with mature cancer cells and revealed that bCSCs displayed a limited level of RS due to a constitutive activation of BMI1/RAD51 axis." (PMID 35110528, 2022). "The absence of RAD51 in the nucleus makes cancer cells unable to repair damaged DNA, potentially leading to synthetic lethality." (PMID 35955488, 2022). "In TMB and MSI analysis, most of the cancer types were not correlated to the RAD51 level, except for the TMB of 6 cancer types which were weakly correlated to the RAD51 level." (PMID 35359409, 2022). "To investigate the expression of RAD51 at the protein level, we compared RAD51 protein staining of cancer and noncancer tissue across 15 tissue types." (PMID 35359409, 2022). "For instance, inhibitors of RAD51 and WRN sensitize cancer cells to DNA damaging agents." (PMID 36569948, 2022). "In this context, new approaches to pharmacologically inhibit RAD51 can not inhibit the cells proliferation of cancer cells." (PMID 35359409, 2022). "In the cancer pathway, cell-cycle gene cyclin A1 and cyclin D1 were upregulated, while tumor proliferation and metastasis pathway FAK-PI3K and Ras-PI3K were upregulated; DNA damage repair-related gene RAD51 was also upregulated." (PMID 36090994, 2022). "Increased expression of RAD51 is a negative prognostic marker for adenocarcinoma and other cancers, but its role in maintaining replication fork speed under basal conditions has not previously been analyzed." (PMID 35969531, 2022). "Several studies demonstrated that unlike normal cells, RAD52 is required for the survival of cancer cells with loss-of-function mutation in genes such as BRCA1, BRCA2, PALB2, and RAD51 paralogs." (PMID 35463312, 2022). "Moreover, the correlations of RAD51 to cancer stemness, TMB, and MSI were also analyzed across different cancer types." (PMID 35359409, 2022). "Since studies demonstrated that DDR proteins may be potentially targeted for cancer therapy, thus, it would be important to locate a drug that can specially target RFWD3-dependent Rad51 ubiquitination for cancer therapy." (PMID 33842359, 2021). "Indeed, several studies proposed that the depletion or pharmacological inhibition of BRD4 directly impacted the expression of HR genes, such as RAD51, BRCA1 and BRIP1, and enhanced the sensitivity of cancer cells to PARP inhibitors." (PMID 34208195, 2021). "Overexpressed Rad51, BRCA1, and MDC1 contribute to genomic integrity and chemoresistance in cancer." (PMID 34025420, 2021). "RAD51 knockdown also sensitized BRCA-proficient MDA-MB-231 and SUM159 cells to olaparib, implying that a combination of RAD51i and PARPi can be used as a strategy to target HR-proficient cancers." (PMID 34208492, 2021). "The central importance of the BRC repeat–RAD51 interaction to HDR has prompted the identification of small-molecule and peptidic inhibitors that might have therapeutic value for cancer treatment." (PMID 33662256, 2021). "Finally, it is not known whether these few RAD51 mutations are actually causal for cancer." (PMID 34316706, 2021). "Thus, chemical inhibition of the protein-protein interaction between BRCA2 and RAD51 disrupts HDR and potentiates DNA damage-induced cell death, with implications for cancer therapy." (PMID 33662256, 2021).
cancer (continued). "Although RAD51 is not (or is rarely) found to be inactivated in cancer, its overexpression has been described in a wide variety of cancers, leading to poor prognosis." (PMID 34316706, 2021). "Given estimates that the SCF complex targets hundreds to thousands of proteins, it is possible that the aberrant regulation (i.e., turnover) of additional protein substrates, such as P27, RAD51, c-MYC may also contribute to cancer pathogenesis." (PMID 35008511, 2021). "Additionally, the preliminary results of the clinical trials on RAD51 inhibitors, such as B02, DIDS, and RI-1, suggest that they can improve the sensitivity of cancer cells to chemotherapeutic drugs when used as adjuvants." (PMID 34575923, 2021). "Therefore, the function of RAD51 is critical to the HR repair efficiency and is correlated with CDDP resistance in cancer cells." (PMID 33397362, 2021). "Indeed, we observed the substantial decrease of half-life of Rad51 in GIST cells treated with CHX in presence of MK-2206, thereby suggesting about the rapid turnover of protein in AKT-inhibited cancer cells." (PMID 33266502, 2020). "The six hub genes (BIRC5, TOP2A, FANCI, NCAPG2, RAD51, and RRM2) were reported to be critical to regulate cell cycle, and their abnormal expression could lead to development and progression of cancers." (PMID 32902196, 2020). "Most likely, it is due to the ability of Rad51 overexpressing cells to increase HRR and by this protect DNA in replication fork stalling to cope with an increased level of double-strand DNA breaks as often observed in cancer cells." (PMID 32719412, 2020). "Contrary to BRCA2 that promotes Rad51-dependent recombination, gene amplifications rather than mutations have been observed for RAD52 in cancer cells." (PMID 32355220, 2020). "The importance of mechanisms that regulate RAD51 protein levels is underscored by studies that have identified increased RAD51 protein levels as a negative predictor of patient outcome in several cancer types." (PMID 30735491, 2019). "Despite the abundance of results, there is still no unequivocal explanation of the role of RAD51 in cancer formation." (PMID 30728902, 2019). "In spite of the abundance of results, there is still no unequivocal explanation of the role of RAD51 in cancer formation." (PMID 30712190, 2019). "The five classical RAD51 paralogs [RAD51B, RAD51C, RAD51D, XRCC2 and XRCC3] are important components of the homologous recombination pathway that preserves genomic integrity and protects against cancer." (PMID 31584931, 2019). "Our results demonstrate that similar to the previously reported RAD51 and RAD51C promoters, pXRCC2-DTA may also serve as a valuable tool for cancer therapy." (PMID 29549248, 2018). "Inhibitors stimulating the formation of toxic RAD51 complexes exploit the upregulation of RAD51 (by enhancing filament stability) targeting cancer cells constitutively overexpressing RAD51 and sparing non-tumour cells." (PMID 29757235, 2018). "Here, we report on the performance of the RAD51 assay in FFPE cancer samples without prior patient treatment or exogenous DNA damage induction and show its correlation with PARPi sensitivity." (PMID 30377213, 2018). "Because RAD51 and RAD51C are highly expressed in some cancer cell types, we hypothesized additional HR factors may also be upregulated in cancer cells and could represent valuable tools for transcriptionally targeting." (PMID 29549248, 2018). "Similar to RAD51 and RAD51C, the XRCC2 promoter is hyperactivated in the group of cancer cells." (PMID 29549248, 2018).
cancer (continued). "Our results suggest that resveratrol is effective to sensitize cervical CSC because of RAD51 inhibition, targeting high RAD51 expressing CD49f-positive cells, which supports the possible therapeutic application of RES as a novel agent to treat cancer." (PMID 29681946, 2018). "Indeed, the promoters of RAD51 and RAD51C17,18, two essential genes involved in HR repair, have been investigated for their potential to transcriptionally target cancer cells." (PMID 29549248, 2018). "The functional biomarker RAD51 enables the identification of PARPi‐sensitive BC and broadens the population who may benefit from this therapy beyond BRCA1/2‐related cancers." (PMID 30377213, 2018). "Estimates of the half-life of RAD51 protein range from 5.5 to ~24 h in primary fibroblast and cancer cell lines, with no clear difference between cell types." (PMID 29254481, 2017). "The shift from RAD51 to MRE11A in SSA/Ps might indicate an increased genomic instability, the key change in all cancer cells." (PMID 29284484, 2017). "Interestingly, expression of RAD51, a key protein involved in homologous recombination (HR), was suppressed while XRCC1 was up-regulated in oleandrin treated cancer cells." (PMID 27449097, 2016). "The use of PARP enzyme inhibitors in cancer cells which are defective for BRCA1 and BRCA2, two proteins that localize the RAD51 recombinase to the sites of damaged DNA and promote HR repair, represent the best and most successful synthetic lethal approach in cancer therapy." (PMID 27884198, 2016). "In addition, expression of Ku 70 and Ku 80 is highly dependent on the genotype of the cancer such as BRCA1, HER2 and RAD51 status." (PMID 26252900, 2015). "Although no clinical trial involving RAD51 inhibitors has been initiated, these molecules remain promising in light of a combinatory treatment as well as a potential therapy for hard-to-treat cancers such as CML." (PMID 26610585, 2015). "RI-1 inhibits the nuclear foci of Rad51 at sites of DNA damage and sensitizes various cancer cell types to cross-linking chemotherapy, but did not affect Rad51 protein levels." (PMID 24795863, 2014). "The expression of breast cancer 1, early onset (BRCA1), RAD51, bloom syndrome, RecQ helicase-like (BLM), flap-endonuclease 1 (FEN1), uracil-DNA glycosylase (UNG), damage-specific DNA binding protein 2 (DDB2) and exonuclease 1 (EXO1) were significantly suppressed after 24 h ZEA treatment." (PMID 24788721, 2014). "Although RAD51 also contains promoter-binding sites for c/EBPβ, it is currently not known to regulate RAD51 expression in the cancer setting." (PMID 24811120, 2014). "For example, BRCA2 functions in RAD51 loading and BRCA1 in countering 53BP1-mediated blocking of homologous recombinational (HR)-DNA repair; hence poly (ADP-ribose) polymerase (PARP) inhibitors have been developed and trialled against BRCA-driven cancers." (PMID 24286369, 2013). "We have shown previously that depression of the RAD51 gene function leads to the massive reproductive death of human cancer cells in the absence of genotoxic injuries." (PMID 24245560, 2013). "This suggests that inhibition of F2 (for example RAD54/RAD54B) would be particularly effective to sensitize cancer cells overexpressing F1 components (e.g. RAD51 paralogs, RAD51, RAD52, BRAC2), a non-intuitive insight derived from the mathematical modeling." (PMID 23592964, 2013). "If RAD51 is responsible for IBR2's effect in cells, IBR2 treatment will be phenotypically silent in cells depleted of RAD51, which induces significant lethality in cancer cells." (PMID 23341130, 2013). "RAD51 was downregulated in all those four cancer cell lines tested, suggesting that downregulation of RAD51 by berberine is not unique to ESCC cells." (PMID 21858113, 2011).
cancer (continued). "Recently, Gorbunova and colleagues reported that the full length Rad51 promoter maintains its cancer specificity when taken independent of its natural context and showed that it can drive tumor-selective expression of a reporter gene." (PMID 22174876, 2011). "Moreover, we revealed that high expression of AARS1 promoted RAD51 chromatin accumulation and decreased γH2AX expression in E-resistant cancer cells overexpressing BLM-WT rather than the K24R mutant." (PMID 40634292, 2025). "The mere fact that its inhibition kills cancer cells does not inherently make RAD51 an oncogene." (PMID 39744578, 2025). "Notably, a previous study showed that Polθ inhibitor induces excessive DSB end resection and nonfunctional RAD51 foci, leading to the cell death of PARPi‐resistant cancer." (PMID 36652375, 2023). "For most cancer cases, RAD51 did not have genetic alterations but had abnormal expression levels." (PMID 35359409, 2022). "Thus, direct use of Nanog appears not reliable to impede Rad51 elevation-reduced vulnerability of cancer cells to genotoxic therapies." (PMID 35220392, 2022). "However, we did not observe any significant correlation between sensitivity of cells to olaparib and RAD51 inhibitors, suggesting that response to olaparib does not appear to be a predictive biomarker for RAD51 inhibitor sensitivity in cancer cells." (PMID 35646698, 2022). "Thus, dysfunctionalities of other DDR factors involved in HR-mediated DSB repair, such as RAD51, ATR, ATM, and CHK1/2, are being studied to expand the spectrum of cancer patients that could benefit from PARP inhibitor treatments." (PMID 34363951, 2021). "Finally, inhibition of the RAD51 protein may provide a mechanism to overcome radiation treatment resistance in GBM and other cancers overexpressing RAD51." (PMID 34771522, 2021). "Paradoxically, despite extensive studies, the inactivation of RAD51, which performs the sequence homology search (i.e. the central step of HR that gives the process its name) has not been found to be related to cancer development." (PMID 34316706, 2021). "In this context, the consequences for cancer outcome might depend on the way HR is inhibited and the presence versus the absence of RAD51 protein on damaged DNA." (PMID 34316706, 2021). "Our findings demonstrated increased RAD51 levels correlated with worse patient outcomes clinically, and confirmed our hypothesis that increased repair capacity of DNA damage could be a mechanism of treatment resistance in GBM and possibly other cancers." (PMID 34771522, 2021). "To assess the contribution of HR to DNA DSB repair, we analyzed the proportion of Rad51 positive (Rad51 +) cells in the population of FACS-enriched CD44high/CD166high cancer stem-like (CSC) and non-CSC (CD44low/CD166low) populations of MFR-surviving and their parental NSCLC cells." (PMID 33673439, 2021). "TIGAR is amplified in different cancer types and its down-regulation sensitizes cancer cells to PARP inhibitors through inhibition of the pentose phosphate pathway, increase in ROS and DNA damage, down-regulation of BRCA1/2 and RAD51, and induction of cellular senescence." (PMID 32029455, 2020). "Rad51 overexpression frequently occurs in various cancers, including prostate cancer, breast and lung cancer as well as melanoma and is a negative prognostic marker for the survival of various cancer patients." (PMID 32719412, 2020). "Therefore, the RAD51 expression in cancer, compared to the paired non-tumor tissue, was upregulated by 2.55-fold (p < 0.0001)." (PMID 31973027, 2020). "Moreover, data obtained from fractionation experiment revealed the substantially decrease in Rad51 level in chromatin fraction when cancer cells were treated with Dox in presence of MK-2206 but not with Dox alone." (PMID 33266502, 2020).
cancer (continued). "Importantly, SOX17 transcriptionally down-regulated DNA repair and damage response-related genes including BRCA1, BRCA2, RAD51, KU80 DNAPK, p21, SIRT1, NFAT5 and REV3L in KYSE510 radio-resistant cells to achieve the sensitization effect to anti-cancer treatment." (PMID 30777052, 2019). "This suggests that RES inhibition of RAD51 expression in CSC leading to a decrease in cell viability and increased apoptosis may have very attractive therapeutic implications for the use of RES in cancer treatment." (PMID 29681946, 2018). "Previous reports indicate that the cancer-specific promoters of RAD51 and RAD51C, two critical HR factors, hold great potential for cancer diagnosis and treatment, but whether the two promoters are suitable for transcriptionally targeting every type of tumor has not been analyzed." (PMID 29549248, 2018). "Interestingly, the authors also showed the remnant Rad51 activities in BRCA-mutated tumors, indicating that PARP inhibition alone is not enough to expel BRCA-mutated cancers." (PMID 29152062, 2017). "Consequently, the inhibition of RAD51 and HR pathways could be an effective adjuvant to the current standard treatment of GBM and represent a major advance for difficult-to-treat cancers." (PMID 27495836, 2016). "Moreover, RAD51 could impede the repair of genes, and RUNX1T1 might block the differentiation of cancer cells." (PMID 27484176, 2016). "However, PARP1 inhibition and the subsequent synthetic lethality can be used on other cancers that do not have mutations in BRCA1 or BRCA2 but that have a defect in the HR pathway, including mutations in ATM, Chk2, Rad51, and NBS1." (PMID 24795863, 2014). "However, the mechanism through which Rad51 expression affects the migratory ability of cancer cells has not been elucidated." (PMID 24065387, 2014). "However, despite these studies, the molecular mechanisms of RAD51-mediated cancer progression have not been fully elucidated." (PMID 24811120, 2014). "Thus, the mechanism of increased transcriptional upregulation of RAD51 in cancers has not been fully defined but it is unlikely to involve gene amplifications or fusions." (PMID 24811120, 2014). "They confirmed that Rad51 was present prior to DNA damage, suggesting that rather than contributing to repair, Rad51 could be driving R-loop-mediated genome instability in cancer cells, and promoting tumour biogenesis." (PMID 23795299, 2013). "The full length Rad51 promoter is highly active in cancer cells but not in normal cells." (PMID 22174876, 2011). "In contrast, RAD51 expression was low or absent in normal tissues surrounding the carcinoma." (PMID 21858113, 2011). "Biallelic loss of HRR genes, especially BRCA1, BRCA2, RAD51D, RAD51 C, and PPP2R2 A was linked to higher HRD scores in BRCA-associated cancers, while BARD1, RAD51D, RAD54L, BRCA1, and MRE11 were associated with elevated HRD scores in in other cancer types (non-BRCA cancers)." (PMID 40420266, 2025). "It is possible that the non-canonical properties of RAD51 are manifested when BRCA1 is absent, together with the genomic instability that is enhanced upon absence of WWOX, causes extensive DNA damage, supporting cancer development, and resistance to treatments." (PMID 38499540, 2024). "Numerous studies have shown that HDACi treatment across various cancer cell lines also results in the transcriptional downregulation of genes involved in homologous recombination and nonhomologous end-joining (Ku70, Ku86, DNA-PKcs, RAD51, BRCA1, and BRCA2), which are critical for DSB repair." (PMID 37991020, 2023).